CRP (C-reactive protein)
Diseases named in the same sentence as CRP in open-access papers (continued):
Sharing a sentence is not in itself a finding about the gene and the disease.
carotid atherosclerosis (continued). "Our findings suggested that the combination of the CRP and Lp‐PLA2 levels might be a useful measure for vascular risk assessment and could be a potential therapeutic target for carotid atherosclerosis." (PMID 30094934, 2018). "Along with such well-known risk factors as old age and higher hs-CRP level, increased E/E’ ratio was an important predictor suggesting the presence of carotid atherosclerosis in non-diabetic CKD patients." (PMID 24192205, 2013). "Age, hs-CRP level, and E/E’ ratio could be significant determinants suggesting the presence of subclinical carotid atherosclerosis in these patients." (PMID 24192205, 2013). "Increased age, hs-CRP level, and E/E’ ratio may be useful markers suggesting the presence of carotid atherosclerosis in these patients." (PMID 24192205, 2013). "However, there was only a minor attenuation of the relative SEP gradient in carotid atherosclerosis after adjustment for CRP." (PMID 18518944, 2008). "Furthermore, elevated serum levels of C-reactive protein (CRP) have been correlated with carotid atherosclerosis, attributable to CRP’s role in enhancing plasminogen expression, facilitating the adhesion of molecules to endothelial cells, and augmenting macrophage LDL phagocytosis." (PMID 38675679, 2024). "Therefore, given that serum N-MID levels were significantly associated with CRP and TG levels and the strong relationship of serum N-MID with carotid atherosclerosis risk, N-MID can be considered as a promising candidate for risk assessment and a potential intervention target for CVD." (PMID 35548441, 2022). "This research shows that high levels of TOS, LHP, 8-IP, MDA, MCP-4, AA, hs-CRP, and TNF-α are associated with severe coronary and carotid stenosis suggesting a possible roles of oxidative stress and inflammatory mediators in the development of coronary and carotid atherosclerosis." (PMID 34976297, 2021). "However, an unequivocal association between hs-CRP values and the carotid atherosclerosis has not been identified yet." (PMID 34829465, 2021). "Additionally, metagenomes analysis of individuals with symptomatic carotid atherosclerosis showed that gene expression of butyrate-synthesizing enzyme (butyrate-ace- toacetate CoA-transferase) were inversely correlated with C reactive protein (CRP) levels." (PMID 35185553, 2021). "Our results, even if preliminary, indicate that intraplaque rather than systemic CRP might be a proatherosclerotic factor potentially useful to better assess the CV risk in patients suffering from severe carotid atherosclerosis." (PMID 27738391, 2016). "The population-based Rotterdam Scan Study evaluated 1033 nondemented elderly individuals and showed that higher CRP levels were associated with presence and progression of leukoaraiosis, independent of cardiovascular risk factors and the degree of carotid atherosclerosis." (PMID 24587705, 2014). "Indeed, the relationship between carotid atherosclerosis and CRP levels were not significant after adjustment for other risk factors in some studies." (PMID 22701780, 2012). "In elderly populations and among patients with heart disease and carotid atherosclerosis, GDF-15 levels are related to circulating markers of inflammatory activity as CRP." (PMID 39780955, 2024). "However, despite the fact that OCN might be the potential link between carotid atherosclerosis and inflammation (CRP), the mechanism by which OCN reflects the changes of CRP in the atherosclerotic pathology remains to be unknown, and future investigations are needed to make it clarified." (PMID 30186852, 2018). "Serum GRB2 was found to be positively correlated with C-reactive protein and interleukin-6 levels, which were higher in patients with T2DM (compared to the healthy population), and further increased in patients with T2DM with carotid atherosclerosis." (PMID 39408563, 2024).
carotid atherosclerosis (continued). "Our study further displayed that CRP levels were remarkably lower in subjects with carotid atherosclerosis compared with those without carotid atherosclerosis and clearly decreased across the serum UCB quintiles." (PMID 36407305, 2022). "Furthermore, C-reactive protein (CRP) levels were significantly higher in the subjects with carotid atherosclerosis than in those without carotid atherosclerosis and clearly decreased across the UCB quintiles." (PMID 36407305, 2022). "Besides CRP, novel biomarkers like matrix metalloproteinases (MMPs) 3,7, and 9 and the tissue inhibitors of metalloproteinase (TIMP)-1 are elevated in those with carotid atherosclerosis, and the elevation of those biomarkers parallel with the percentage of carotid artery stenosis." (PMID 38248862, 2024). "Finally, other inflammatory markers aside from CRP, fibrinogen, and D-dimers, as well as other atherosclerotic macrovascular diseases including aortic atherosclerosis, thoracic or abdominal aortic aneurysm, and carotid atherosclerosis were not evaluated in this study." (PMID 34278285, 2021). "In the present study, we examined the relationship among carotid atherosclerosis, the apoB/apoAΙ ratio, and the non-HDL-C/HDL-C ratio, as well as conventional lipids, IR, and C reactive protein (CRP), among Chinese individuals with MetS." (PMID 25885111, 2015).
polycystic ovary syndrome (63 papers, 2008 to 2026). A disorder that manifests as multiple cysts on the ovaries. "Further studies are required to determine the underlying cause of increased C-reactive protein levels among women with polycystic ovary syndrome." (PMID 38397957, 2024). "Polycystic ovary syndrome is associated with a marked increase in inflammation biomarkers such as C-reactive protein (CRP), IL-18, and MCP-1, and is also associated with other inflammation-related disorders." (PMID 39768981, 2024). "Reports have shown that patients with polycystic ovary syndrome exhibit elevated levels of CRP, and this indicator is associated with infertility as well as diabetes and cardiovascular disease." (PMID 37660067, 2023). "Metformin significantly reduces CRP in women with polycystic ovarian syndrome (PCOS), a disease that is associated with HS." (PMID 37108132, 2023). "We are hereby investigating for the first time the effect of the association ethinylestradiol30μg-drospirenone 3mg (DRP/EE30μg) plus metformin and weight loss on endothelial status and C-reactive protein (hsCRP) levels in polycystic ovary syndrome (PCOS)." (PMID 22713099, 2012). "Considering that polycystic ovary syndrome is associated with low-grade chronic inflammation, increased CRP levels can be expected in PCOS patients." (PMID 40572700, 2025). "It has been revealed that there is a strong connection between inflammation and polycystic ovary syndrome in which high levels of C-reactive protein are considered a sign of evoked inflammatory response, along with other inflammatory cytokines, such as IL-6." (PMID 38397957, 2024). "It was also observed that plasma C-reactive protein levels were negatively correlated with the plasma levels of oncostatin M in patients with polycystic ovary syndrome." (PMID 38397957, 2024). "Oncostatin M levels were significantly lower, but C-reactive protein levels were substantially higher in the polycystic ovary syndrome group than in the control group (p = 0.002, p = 0.001, respectively)." (PMID 38397957, 2024). "Recent studies have also revealed a marked reduction in C-reactive protein levels with metformin treatment in patients with polycystic ovary syndrome." (PMID 38397957, 2024). "Multiple studies have shown that C-reactive protein levels are increased in patients with polycystic ovary syndrome." (PMID 38397957, 2024). "Another double-blinded study in 2015 found that after an 8-week intervention of 50 mg zinc daily, patients with polycystic ovary syndrome consumed only had a significant trend on reduced CRP levels." (PMID 35211497, 2022). "The impact of the recommended first-line treatment with metformin on C-reactive protein (CRP) levels in patients with polycystic ovary syndrome (PCOS) is still controversial." (PMID 28404960, 2017). "In this PCOS cohort, there was increased BMI, IR and systemic inflammation with increased CRP and hyperandrogenemia that may have worked in concert to negatively affect bone compared to that of the normal control population." (PMID 41226313, 2025). "Based on elevated C-reactive protein levels, it could be concluded that patients with polycystic ovary syndrome may have chronic low-grade inflammation." (PMID 38397957, 2024). "Regarding chronic low-grade inflammation in polycystic ovary syndrome, most of the articles in the literature have revolved around C-reactive protein, an acute-phase protein produced by the liver in response to interleukin-6 and tumor necrosis factor stimulation." (PMID 38397957, 2024). "In another study evaluating obese women with polycystic ovary syndrome, vitamin D deficiency was found to be associated with higher depressive symptoms and higher CRP, independent of polycystic ovary syndrome presence." (PMID 26217190, 2015).
polycystic ovary syndrome (continued). "Notably, a study of effects of magnesium and vitamin E co-supplementation on hormonal status and biomarkers of inflammation and oxidative stress in women with polycystic ovary syndrome demonstrated that co-supplementation for 12 weeks significantly decreased serum hs-CRP levels." (PMID 40959697, 2025). "Polycystic ovary syndrome (PCOS) exhibit a metabolic component consisting of higher plasma CRP levels, hyperinsulinemic and hyperleptinemia." (PMID 37660067, 2023). "Oral administration of rosiglitazone 4 mg once a day for three months improves hyperandrogenemia, insulin resistance, lipidemia, C-reactive protein levels, ovarian volume, and follicle number in patients with polycystic ovary syndrome (PCOS)." (PMID 32028670, 2020). "Polycystic ovary syndrome (PCOS) is one of the most common diseases among women associat-ed with various inflammatory reactants such as C-reactive protein (CRP) and ferritin." (PMID 22737516, 2011). "Studies have indicated that individuals with polycystic ovary syndrome exhibit elevated levels of inflammatory markers such as TNF, IL-6, CRP, IL-18, IL-1β, and white blood cell counts." (PMID 40933264, 2025). "In polycystic ovary syndrome, C1QTNF6 upregulates serum levels of proinflammatory factors, such as C-reactive protein (CRP), interleukin 6 (IL-6), and tumor necrosis factor-α (TNF-α)." (PMID 36052307, 2022). "Another study found reduced high sensitivity-C-reactive protein (hs-CRP) of 27 women with polycystic ovary syndrome (PCOS) during the Ramadan period in Iran and in which participants aged 18 to 40 years old with an average of age 27.5, followed everyday 16.5 h fasting, isocaloric diet, for 29 days." (PMID 32531935, 2020). "In disorders like polycystic ovary syndrome, MHR was found to be more sensitive than the usual markers such as increased BMI and C-reactive protein (CRP) in predicting disease development." (PMID 33396346, 2020). "This study aimed at investigating the therapeutic effects of curcumin on IL-6, CRP and TNF-α and symptoms of polycystic ovary syndrome." (PMID 29201665, 2017). "In the age- and nonobese-BMI-matched cohort with and without PCOS, these PCOS women did not have IR or systemic inflammation (as CRP was not elevated), but did have hyperandrogenemia." (PMID 41226313, 2025). "For the nonobese, non-insulin-resistant cohort, age and BMI were matched, and the women with PCOS were not insulin-resistant nor was their CRP elevated, but they did have hyperandrogenemia." (PMID 41226313, 2025). "Although all inflammatory cytokines in this study were not examined, it was revealed that C-reactive protein levels were notably elevated in patients with polycystic ovary syndrome compared to the control group." (PMID 38397957, 2024). "Although the majority of authors have obtained similar results, in the available literature there are papers in which researchers have not shown higher CRP values in patients with polycystic ovary syndrome." (PMID 37509592, 2023). "Metabolic effect differences were found between fish (a source of EPA/DHA) and flaxseed oil (a source of ALA) on glucose homeostasis, but not on CRP or lipid metabolism in a primarily Caucasian cohort of women with polycystic ovary syndrome." (PMID 31667003, 2013). "Hyperandrogenemia did not correlate with CRP or complement in non-obese PCOS." (PMID 40243681, 2025). "Having low-grade chronic inflammation such as elevated C-reactive protein (CRP), interleukin-6 (IL-6) and tumor necrosis factor-α (TNF-α) plays a crucial role in polycystic ovary syndrome (PCOS)." (PMID 29201665, 2017). "We aimed to estimate the glomerular filtration rate (GFR) in women withpolycystic ovary syndrome (PCOS) and to determine the relationship between GFR withC-reactive protein (CRP) and uric acid." (PMID 26246875, 2015).
polycystic ovary syndrome (continued). "In this study, we demonstrated that serum chromogranin A (CgA) levels were significantly elevated in women with polycystic ovary syndrome (PCOS) and showed a positive correlation with body mass index (BMI), insulin, glucose, HOMA-IR, and high-sensitivity C-reactive protein (hs-CRP)." (PMID 41480370, 2025).
venous thromboembolism (63 papers, 2014 to 2026). Occlusion of the lumen of a vein by a thrombus that has migrated from a distal site via the blood stream. "Although the associations between CKD and venous thromboembolism are unclear, body mass index, C-reactive protein and D-dimer levels have been reported as biomarkers." (PMID 39951307, 2025). "As a result, fibrinogen levels were 1.3-fold lower (p=0.0270), while CRP levels were 3.1-fold higher (p=0.0051) in LC participants, alterations that have been previously linked to a higher risk of venous thromboembolism." (PMID 41181095, 2025). "Our review found that the associations of CRP with cardiovascular mortality and venous thromboembolism were supported by strong evidence." (PMID 32978716, 2021). "Only two outcomes, cardiovascular mortality and venous thromboembolism, showed convincing evidence of association with CRP levels." (PMID 32978716, 2021). "Multivariable analysis identified venous thromboembolism (OR 5.1), pathologic platelet count (OR = 2.9), low hemoglobin (OR 2.5) and elevated CRP (OR 1.8) as independently associated with cancer." (PMID 33945004, 2021). "A meta-analysis of nine studies also provides evidence on the dose-dependent relationship of CRP and increased risk of venous thromboembolism." (PMID 33101164, 2020). "This study assessed D-dimer (DD) and high-sensitivity C-reactive protein (hs-CRP) levels after the withdrawal of anticoagulation treatment to predict the risk of venous thromboembolism (VTE) recurrence among patients with CAT." (PMID 30318508, 2018). "Whilst levels of CRP seem to be independently associated with a significant risk of cardiovascular disease, their role in predicting venous thromboembolism (VTE) is still controversial." (PMID 26848624, 2016). "We suggest to further investigate the impact of OC-related CRP increase on the risk of venous thromboembolism, including the association between LGI and the various generations of OC." (PMID 24516611, 2014). "CRP played an important role in inflammation, the tissue factor (TF) pathway, blood coagulation, endogenous fibrinolytic capacity, and the susceptibility of venous thromboembolism." (PMID 35721727, 2022). "Among the 10,505 participants in the ARIC (Atherosclerosis Risk in Community) who were followed for incident deep venous thrombosis or APE over a period of 8.3 years, an increase in CRP concentration above the 90th percentile was associated with a 76% increased risk of venous thromboembolism." (PMID 31936687, 2020). "Evolving debate suggests that C-reactive protein (CRP) might be associated with the development of venous thromboembolism (VTE); however, the evidence is conflicting." (PMID 28718029, 2017). "Patients admitted to the IBD specialty centre were more likely to receive baseline CRP measurement, venous thromboembolism prophylaxis, and treatment with intravenous steroids and biologic therapy during their admission." (PMID 40900917, 2025). "By utilizing advanced algorithms such as LR, RF, and GBM, we effectively identified fibrinogen, vWF, FVIII, and CRP as predictive factors for venous thromboembolism in patients with MM." (PMID 39960959, 2025). "In addition, a higher risk of venous thromboembolism has been reported in patients with c-reactive protein flares early after ICI administration, and increased secretion of various cytokines associated with inflammatory responses may contribute to coagulation abnormalities." (PMID 40980112, 2023). "A recent study also reported that C-reactive protein (CRP), a marker of acute inflammation, had predictive value for venous thromboembolism." (PMID 33532130, 2021). "C-reactive protein, a well-known marker of inflammation and tissue damage, was extensively studied in venous thromboembolism and had a sensitivity ranging 60% and 100% at the level between 5 mg/L and 10 mg/L and specificity varying between 52% and 78%." (PMID 31936687, 2020).
venous thromboembolism (continued). "While there is strong evidence that CRP is a predictor of arterial thrombotic events, conflicting clinical data exists on the relationship between increased plasma CRP concentration and venous thromboembolism (VTE)." (PMID 31151201, 2019). "A further aim was to evaluate the potential role of hs-CRP in predicting a cardiovascular event, in particular, venous thromboembolism (VTE)." (PMID 26848624, 2016). "Univariate logistic regression analysis indicated that age, spontaneous echo contrast (SEC), C-reactive protein (CRP), fibrinogen, Albuminumin, creatinine and uric acid had a statistically significant impact on the incidence of venous thromboembolism (VTE), with the exception of D-dimer." (PMID 40534751, 2025). "Observational studies presented robust evidence of association between higher CRP levels and cardiovascular mortality and venous thromboembolism, but without causality support from MR studies." (PMID 32978716, 2021). "Nonetheless, only two of these associations had strong results with no suggestions of biases (cardiovascular mortality and venous thromboembolism in general population) and none of these had supporting evidence of a causal role for CRP in MR investigations." (PMID 32978716, 2021). "CRP levels in patients with VTE were between normal values (0.11 mg/dL) but significantly lower when compared to the first measure with 3-year median after venous thromboembolism episode (0.21 mg/dL; P = 0.003)." (PMID 25782371, 2015). "The mean hs-CRP level of participants was significantly higher than cut-point of 10 mg/L; this result may demonstrate the existence of inflammation as a promoting factor of thrombosis in patients with venous thromboembolism." (PMID 24734087, 2014). "One of these tested serological markers, D-Dimer, which was traditionally used for venous thromboembolism (VTE) detecting, recently has been demonstrated as a promising marker and to perform better than CRP and ESR in PJI diagnosis." (PMID 31783874, 2019). "This antiphospholipid antibody was also related to venous thromboembolism, and respiratory disease (declining oxygen requirement) in the absence of systemic inflammation (CRP)." (PMID 34401683, 2021). "Differences between these groups were observed for history of venous thromboembolism, family history of cancer, and selected laboratory parameters including higher levels of D-dimers, ESR, CRP, pathologically low or high levels of platelets and lower levels of hemoglobin associated with cancer." (PMID 33945004, 2021).